RECQL4 (RecQ like helicase 4)
Diseases named in the same sentence as RECQL4 in open-access papers (continued):
Sharing a sentence is not in itself a finding about the gene and the disease.
tumor (continued). "Sig27var25 and SigIQvar8 are highly effective at predicting ACC prognosis and progression; both signatures contain component genes predicting poor OS independently of age and tumor stages, for instance SNHG10 and RECQL4 for SigIQvar8 as well as MXD3, BIRC5, and RAB30 for Sig27var25." (PMID 35681785, 2022). "In the HPA data, compared with normal tissues, the expression of PKMYT1, ETF1, RECQL4, TUBB2B, and CDC6 in tumor tissues was remarkably upregulated, while the expression of TFRC and PITX1 was significantly downregulated (,ECT2, BUBB1B, and COCH were not included)." (PMID 33869220, 2021). "RECQL4 was highly expressed in tumor tissues when compared to adjacent non-tumor tissues in ESCC (P < 0.001) and positively correlated with poor differentiation (P = 0.011), enhanced invasion (P = 0.033), and metastasis (P = 0.048)." (PMID 33628589, 2021). "Clonogenic cell lines with stable suppression of RecQL4 displayed a markedly reduced tumorigenic potential in vivo with an absolute lack of tumor growth in 4 out of 7 nude mice xenografts." (PMID 23894508, 2013). "Not all but some of the genes as MCM4, MCM6, MCM10 and RECQL4 show a positive trend with increasing tumor stages." (PMID 23874974, 2013). "This includes not only serum and immune biomarkers but also tumor-intrinsic biomarkers of immune competence, such as the expression of proteins that regulate key pathways, like cGAS-STING (e.g., RECQL4, TRIM6), which may stratify patients who are likely to need additional innate immune agonists." (PMID 41295487, 2025). "In contrast, RECQL4 expression was low or absent in adjacent non-tumor tissues (P < 0.001)." (PMID 33628589, 2021).
genetic disorders (13 papers, 2011 to 2023). "Mutations in WRN, BLM, or RECQL4 cause different genetic disorders, all associated with accelerated aging, genomic instability and tumorigenesis." (PMID 32820027, 2020). "Gene mutations of RECQL2, RECQL3, and RECQL4 are associated with genetic disorders and induce early aging and carcinogenesis." (PMID 25424877, 2014). "Consequently, it remains unclear if defective RECQL4 helicase activity in humans per se is implicated in any of the three RECQL4-linked genetic disorders." (PMID 32120966, 2020).
adenocarcinoma (4 papers, 2019 to 2024). A common cancer characterized by the presence of malignant glandular cells. "The present results also exhibit that among the amplified genes, the following eight genes involved in the cell cycle were found to be amplified in more than 5% of HGSO adenocarcinoma patients: ATAD2, ASF1B, CCNE1, CDC20, CDCA8, RECQL4, RNASEH2A, and SMC4." (PMID 39199556, 2024). "To conclude, our comprehensive analyses identified PTP4A3, NAPRT, and RECQL4 were co-amplified and co-expressed specifically in LEP/MIP adenocarcinoma, and RECQL4 was upregulated in the MIP group." (PMID 35992814, 2022).
infection (2 papers, 2015 to 2021). The state of being infected such as from the introduction of a foreign agent such as serum, vaccine, antigenic substance or organism. "The WCP data suggest that each of the selected proteins (HELLS/SMARCA6, RECQL4, SQSTM1, and DCAF1) are decreased during Ad5 WT infection, with distinct abundance change profiles." (PMID 34463575, 2021). "Infection with AdΔE4 allowed us to implicate a significant role for the E4 cassette in the degradation of the host factors DCAF1, RECQL4, SMARCA6, and SQSTM1." (PMID 34463575, 2021). "The decreases in abundance observed for HELLS/SMARCA6, RECQL4, SQSTM1/p62, and DCAF1 during Ad5 WT infection were mitigated during AdΔE4 infection, suggesting that manipulation of these proteins is dependent on one or more E4 gene products." (PMID 34463575, 2021). "Proteins in this category that exhibited decreases during infection included the SWI/SNF protein family member Lymphoid-specific helicase (HELLS/SMARCA6/LSH) and the ATP-dependent DNA helicase Q4 (RECQL4)." (PMID 34463575, 2021). "The immunoblot data also show that HELLS/SMARCA6, RECQL4, SQSTM1/p62, and DCAF1 each exhibit decreased protein abundances during Ad5 WT infection, consistent with the WCP data." (PMID 34463575, 2021).
CNS tumors (1 paper, 2025). "Across 1580 CNS tumors, RECQL4 gene variants were identified in 71 cases (4.5%), with 21 (29.6%) of probable pathogenic significance." (PMID 41317405, 2025).
nervous system tumors (1 paper, 2025). "We found RECQL4 gene variants in 4.5% nervous system tumor cases, and a proportion (29.6%) of these of probable pathogenic (loss of function) significance." (PMID 41317405, 2025).
RECQL4 also shares sentences with these, for which no sentence is quoted: lymphoma (5 papers); Alzheimer disease (2); Intellectual disability (2); leukemia (2); Li-Fraumeni syndrome (2); 22q11.2 deletion syndrome (1); alopecia (1); AMeD syndrome (1); anemia (1); atypical teratoid rhabdoid tumor (1); benign neoplasm (1); Berardinelli-Seip congenital lipodystrophy (1); bowel cancer (1); cataract (1); COVID-19 (1); cryptorchidism (1); dental disorder (1); Diamond-Blackfan anemia (1); dwarfism (1); dysplastic nevi (1); ectodermal dysplasia (1); ependymoma (1); epidermolysis bullosa simplex (1); epilepsy (1); Erythema (1); esophageal cancer (1); familial breast cancer (1); hearing loss (1); Hutchinson-Gilford progeria syndrome (1); insomnia (1).
A further 37 diseases each share a sentence with RECQL4 in 1 paper.